ENSG00000258466 (novel protein)
Gene: Protein-coding gene on chromosome 14 (67,659,820 to 67,690,367, reverse strand). Ensembl gene ENSG00000258466.
Genetic constraint (gnomAD): Missense variants: 125 observed, 147.82 expected, observed/expected ratio (o/e) 0.85, 90% interval 0.73 to 0.98. Synonymous variants: 57 observed, 59.33 expected, observed/expected ratio (o/e) 0.96, 90% interval 0.78 to 1.2.